NGF (nerve growth factor)
Diseases named in the same sentence as NGF in open-access papers (continued):
Sharing a sentence is not in itself a finding about the gene and the disease.
Hyperglycemia (33 papers, 2010 to 2025). An increased concentration of glucose in the blood. "Hyperglycemia is also associated with neural invasion and increased secretion of nerve growth factor (NGF) that ensure a loop of further neural infiltration and tumor growth." (PMID 36829437, 2023). "To identify the effect of TFP5 and NGF on renal function damage caused by hyperglycemia in db/db mouse model, we treated mice with TFP5 peptides, K252a, or both." (PMID 35874807, 2022). "Also, risk of hyperglycemia was considerably lower among the participants only in the second tertile of serum NGF compared to the reference group." (PMID 35620753, 2022). "Risk of hyperglycemia was significantly lower among the participants only in the second tertile of serum NGF compared to the reference group in both crude and adjusted models (OR = 0.278, 95% CI: 0.091-0.845 vs. OR = 0.240, 95% CI: 0.074-0.779, P trend = 0.130)." (PMID 35620753, 2022). "Persistent hyperglycemia increased ROS generation, and increased advanced glycation end products cause neuronal damage via increasing leukocytic infiltration and reduction in nerve growth factor (NGF)." (PMID 34149415, 2021). "Our observation of increased staining of p75NTR in the hyperglycemia group indicated dysfunction or demyelinization of the affected nerve sheaths and was consistent with a previous report suggesting that excessive NGF may cause apoptosis via p75NTR." (PMID 21386984, 2011). "Hyperglycemia also leads to corneal nerve degeneration and reduced nerve growth factor (NGF) levels, impairing corneal sensation and repair capacity." (PMID 39807180, 2025). "Hyperglycaemia rapidly augments vascular NGF release, activates β-cell TrkA and amplifies glucose-stimulated insulin secretion (GSIS)." (PMID 41471293, 2025). "Hyperglycemia impedes Schwann cell secretion of nerve growth factor (NGF) and neurotrophin 3 (NT3), curtailing the neurotrophic support essential for axonal health and impeding regeneration." (PMID 40264787, 2025). "Together these findings suggest an NGF/Sirt1 axis where NGF upregulates Sirt1 to maintain autophagy and cell survival, conversely, hyperglycemia-driven Cdk5 activation suppresses NGF, impairing autophagy." (PMID 41471293, 2025). "As fetal macrosomia is usually the result of fetal hyperglycemia due to maternal gestational diabetes, it was important to measure NGF levels in amniotic fluid in our study so as to draw conclusions concerning fetal NGF levels." (PMID 37373824, 2023). "Hyperglycemia attenuates the expression of nerve growth factor (NGF) and glial cell-derived nerve growth factor (GDNF) in the corneal epithelium, while exogenous NGF and GDNF increased the sub-basal nerve fiber density and corneal sensitivity." (PMID 36589805, 2022). "Recent evidence has suggested that chronic hyperglycemia contributes to downregulating target-derived nerve growth factor (NGF), which is a trophic factor essential for the survival of small-diameter primary sensory neurons and autonomic nerves." (PMID 36210810, 2022). "We have previously shown that, exposure to hyperglycemia disturbed homeostasis of NGF by accumulation of its precursor; proNGF at the expense of the mature form; NGF11,28." (PMID 30131506, 2018). "Hyperglycemia-induced downregulation of neurotrophic mediators such as nerve growth factor (NGF), pigment epithelium-derived factor (PEDF), iron-responsive element-binding proteins (IRBP) and somatostatin, also contributed to neurodegeneration." (PMID 29301251, 2018). "The percentage of cancer area occupied by positive NGF staining cancer cells was significantly higher in the hyperglycemia group than in the euglycemia group." (PMID 21386984, 2011). "Our data demonstrated that NGF-positive cancer cells were evident and coincident with the improved nerves in the hyperglycemia group." (PMID 21386984, 2011). "NGF protects diabetic animals from hyperglycaemia-induced neuronal damage by upregulating Sirt1." (PMID 41181709, 2025).
Hyperglycemia (continued). "Concomitantly, NGF triggers an anti-inflammatory response in surface inducing production of IL-1 receptor antagonist and IL-10 and dampens NF-κB activation, thereby reducing hyperglycemia-driven corneal inflammation." (PMID 41471293, 2025). "In addition, formononetin protects diabetic rats from hyperglycaemia-induced neuronal damage by controlling hyperglycaemia and upregulating NGF and Sirt1 in nerve tissues." (PMID 41181709, 2025). "Interestingly, when comparing type 1 with type 2 diabetic patients with similar durations of hyperglycemia and HbA1c levels, type 1 patients tend to have higher NGF levels than those with type 2 diabetes." (PMID 37373824, 2023). "Hyperglycemia-induced overexpression of p75NTR and disrupted homeostasis of NGF and proNGF levels resulted in a significant upregulation of the proNGF/p75NTR pathway in mouse cavernous epithelial cells, accelerating neuronal cell apoptosis and inducing nerve injury." (PMID 37065751, 2023). "In conclusion, TFP5 treatment protects the kidney from hyperglycemia-induced damage by CDK5-NGF-Sirt1 regulation axis, and NGF and Sirt1 may be the novel target for DN." (PMID 35874807, 2022). "Mounting evidence has shown that hyperglycemia induces downregulation of NGF, which may have a central contributing or initiating role in neuronal apoptosis and dropout of capillaries." (PMID 31736682, 2019). "Most importantly, BBR has been demonstrated that it can attenuate hyperglycemia-induced apoptotic death and promote Nrf2-dependent NGF protein expression and neurite outgrowth, providing a potential therapeutic use of BBR on the treatment of diabetic complication." (PMID 27529235, 2016). "The NGF staining in the cytoplasm of the cancer cells was significantly stronger (p = 0.002) in the hyperglycemia group than in the euglycemia group, indicating the NGF protein level of cancer cells was increased in the hyperglycemia group." (PMID 21386984, 2011). "We suggest that hyperglycemia may induce the NGF expression of cancer cells, which regenerates the affected nerves by stimulating axon branching and that NGF may be as potential key player in the generation of pancreatic neuropathy in PanCa." (PMID 21386984, 2011). "The integrated optical density (IOD) of MPP staining was lower in the hyperglycemia group than those in the euglycemia group (p = 0.019), while the expression levels of NGF and p75 were higher in the hyperglycemia group than those in the euglycemia group (p = 0.002, and p = 0.026, respectively)." (PMID 21386984, 2011). "Finally, we found that K252a, an inhibitor of NGF treatment could undermine the protective role of TFP5 on hyperglycemia-induced DN in db/db mouse model." (PMID 35874807, 2022). "Neutralization of NGF attenuates hyperglycemia-induced tumor aggressiveness and nerve-directed invasion, supporting NGF as a key mediator linking diabetic metabolic conditions to exacerbated perineural invasion, rather than indicating a simple loss of NGF signaling." (PMID 41471293, 2025). "Formononetin protects diabetic animals from hyperglycemia-induced neuronal damage by increasing the expression of SIRT1 and NGF in neural tissue." (PMID 34159207, 2021). "We demonstrated that patients with hyperglycemia display reduced expression of MPP, and elevated expression of NGF and p75 in comparison to the patients with euglycemia." (PMID 21386984, 2011). "Both hyperglycemia and STZ treatment increase β cell production of nerve growth factor (NGF)." (PMID 33036983, 2020).
psoriasis (33 papers, 2009 to 2025). An autoimmune condition characterized by red, well-delineated plaques with silvery scales that are usually on the extensor surfaces and scalp. "In an active process of inflammation, NGF expression is markedly upregulated in nerves related to the inflamed area, while increased levels of NGF are associated with skin dermatoses such as psoriasis." (PMID 36902434, 2023). "On the other hand, NGF causes the elongation and branching of epidermal nerve fibers, which leads to hypersensitivity of itch and inflammation aggravation in psoriasis." (PMID 35173615, 2022). "There is evidence that the NGF-TrkA pathway plays a key role in the pathogenesis of psoriasis and associated pruritus." (PMID 31694615, 2019). "NGF is highly upregulated in cutaneous nerves following an inflammation event; NGF has also been linked to psoriasis." (PMID 31441145, 2019). "Various cytokines and adhesion molecules, including interleukin (IL)-1, IL-2, IL-6, IL-8, IL-12, IL-18, TNF-α, and nerve growth factor, are abnormally expressed in the lesions of psoriasis patients, suggesting that psoriasis is associated with the release of NF-κB-regulated inflammatory cytokines." (PMID 36835162, 2023). "The significant association between the NGF expression and psoriasis in comparison to the other angiogenesis growth factors investigated in this study may suggest the potential use of the NGF as an indicator for the development of psoriasis vulgaris." (PMID 22537619, 2012). "However, there may be other factors in addition to NGF that cause nerve fiber changes and itch in psoriasis." (PMID 35173615, 2022). "The role of nerve growth factor in the pathogenesis of psoriasis is further supported by the evidence that inhibition of nerve growth factor receptor with either its blocker or its neutralizing antibody improves psoriasis." (PMID 40861201, 2025). "In patients with pruritic skin diseases including AD, prurigo nodularis and psoriasis, the levels of NGF in the plasma and expression of its receptors TrkA and p75NTR in lesional skin were significantly higher and associated with strong pruritus." (PMID 37555911, 2023). "The results of an observational study have indicated that HPV infection triggers plaque-type psoriasis and illustrated the role of nerve growth factor (NGF) in HPV-induced psoriasis." (PMID 35805960, 2022). "NGF is also significantly expressed in numerous inflammatory skin disorders, such as psoriasis and prurigo nodularis." (PMID 36012289, 2022). "Our results showed that NGF expression levels were significantly upregulated in psoriasis skin lesions." (PMID 35173615, 2022). "Upregulated NGF leads to pathological features of psoriasis, including keratinocyte proliferation, angiogenesis, and T cell activation." (PMID 35805960, 2022). "We assumed that in pruritus psoriasis skin, the number of nerve fibers increases, and the new nerve fibers promote the continued secretion of NGF, resulting in abnormal hyperplasia of nerve fibers and more sensitive sensation." (PMID 35173615, 2022). "By regulating neurogenic inflammation, NGF plays important roles in the development of psoriasis and is related to the intensity of pruritus." (PMID 35054853, 2022). "Since epidermal keratinocytes in psoriasis produce increased levels of NGF, it is logical to assume that this would influence the growth of nerves." (PMID 35321329, 2022). "The role of multiple pruritic mediators have been investigated in psoriasis, including neuropeptides, nerve growth factor, IL-31, and TSLP." (PMID 35321329, 2022). "Elevated NGF-levels were found in AD and psoriasis patients and correlated with the reported itch severity and increased skin innervation." (PMID 34728705, 2021). "In psoriasis, immunoreactivity for NGF is strong throughout the entire epidermis, the expression of TrkA is elevated in basal keratinocytes and dermal nerves, and the expression levels of these proteins correlate with the severity of pruritus." (PMID 33182442, 2020).
psoriasis (continued). "After a cutaneous trauma, in a developing psoriasis lesion, keratinocyte proliferation and up-regulation of NGF in basal keratinocytes are early events and precede epidermotropism of T lymphocytes." (PMID 31491865, 2019). "This study suggests that NGF plays a critical role in the pathogenesis of psoriasis and that the regulatory role of NGF and its receptor system is functionally active in the early stage of developing lesions of psoriasis." (PMID 31491865, 2019). "In our investigation, NGF expression was enhanced, which concurs with the observation in psoriasis patients." (PMID 31294123, 2019). "We have reported that self-scratching behavior in IMQ-induced psoriasis model mice is accompanied by increased number of mast cells and expression of NGF and neuropeptides, which is approximately representative of human psoriasis patients." (PMID 31294123, 2019). "Self-scratching behavior is accompanied by increased number of mast cells and expression of NGF and endogenous pruritogenic peptides in our imiquimod-induced psoriasis model." (PMID 31294123, 2019). "TrkA, the surface transmembrane receptor tyrosine kinase for the neurotrophin, nerve growth factor (NGF), plays an important role in the pathogenesis of psoriasis and associated pruritus." (PMID 31694615, 2019). "In line with the increased expression of Trk and NGF in psoriasis, topical treatment with K252 improves psoriasis in the immunodeficient mouse–human skin model." (PMID 28326307, 2017). "In a developing a psoriatic lesion, the up-regulation of NGF together with keratinocyte proliferation are early events and precede epidermotropism of T lymphocytes; keratinocytes in patients with psoriasis are primed to produce elevated levels of NGF." (PMID 25870676, 2014). "Epidermal keratinocytes have been identified mainly as the source of the VEGF, PlGF, NGF and vWFR that contribute to psoriasis angiogenesis." (PMID 22537619, 2012). "The role of NGF on the development of psoriasis is still poorly understood though related to neurogenic inflammatory nature of the NGF postulation." (PMID 22537619, 2012). "Hence, stress-induced increases in nerve growth factor can contribute, in part, to the pathogenesis of psoriasis." (PMID 40861201, 2025). "In line with this, significantly higher expression levels of NGF and TrkA were found in psoriasis patients with pruritus as compared to patients without pruritus, and the expression levels of NGF and TrkA were associated with pruritus severity." (PMID 37555911, 2023). "NGF can recruit and activate T lymphocytes to promote the inflammatory response in psoriasis." (PMID 35054853, 2022). "NGF and IL-31, which are strongly expressed in the lesional skin of psoriasis, have been shown to promote the growth of sensory nerves, suggesting that the elongation and branching morphogenesis of epidermal nerve fibers are involved in the hypersensitivity of itch in psoriasis." (PMID 33182442, 2020). "As a representative nerve elongation factor, NGF occurs in higher levels not only in the lesional skin patients with AD, psoriasis, prurigo nodularis, contact dermatitis, and xerosis, but also in plasma of AD patients suggesting a useful marker in the diagnostic and treatment." (PMID 26287150, 2015). "Even though the pathophysiology of the Koebner phenomenon has not been entirely elucidated, it was demonstrated that nerve growth factor (NGF) influences the key pathological events in psoriasis and Koebner phenomenon: keratinocyte proliferation, angiogenesis and T-cell activation." (PMID 25870676, 2014). "Indeed, NGF is expressed in endothelial cells and keratinocytes in patients with psoriasis, and NGF and BDNF are present in the inflamed joints of patients with rheumatoid arthritis." (PMID 25418464, 2014).
psoriasis (continued). "Since NGF is known to increase cutaneous innervation in AD models and might contribute to the development of chronic pruritus, NGF and its receptor TrkA could be targets for future treatment of pruritus and allergic inflammation in pruritic diseases like AD or psoriasis." (PMID 33681256, 2021). "Notably, the keratinocytes of patients with psoriasis produce higher levels of NGF." (PMID 31491865, 2019). "Nerve growth factor (NGF)-related reactive oxygen species in wound healing involve the recognition of noticeable NGF higher expression of keratinocytes under angiogenic conditions, such as psoriasis and wound healing." (PMID 36831151, 2023). "Some researchers have observed that compared with nonpruritic skin, NGF content was increased in pruritic psoriasis skin lesions accompanied by increased nerve density in the skin, whereas others did not see such a correlation." (PMID 35173615, 2022). "Some researchers have observed that compared with nonpruritic skin, NGF content in pruritic psoriasis skin lesions was increased and accompanied by increased nerve density in the skin." (PMID 35173615, 2022). "While NGF antibodies are in clinical trials for pain, K252a, the only small molecule TRK-A inhibitor in the clinic, is currently under evaluation for the treatment of psoriasis." (PMID 24386191, 2013). "Notably, elevated nerve growth factor (NGF) levels in the skin and blood have been reported in patients with atopic dermatitis, contact dermatitis, and chronic prurigo, as well as in the pruritic lesions of the patients with psoriasis." (PMID 35890193, 2022). "Furthermore, NGF expression levels were significantly higher in lesional pruritic skin than in non-lesional skin with psoriasis." (PMID 33182442, 2020).